CYP3A51P (cytochrome P450 family 3 subfamily A member 51, pseudogene)
Synonyms: CYP3A5-de13c; CYP3A5-de1b2b; CYP3A5P1; CYP3AP1
Gene: Unprocessed pseudogene on chromosome 7 (99,685,145 to 99,700,034, reverse strand). Ensembl gene ENSG00000282277.
Diseases named in the same sentence as CYP3A51P in open-access papers:
CYP3A51P is named in the same sentence as 3 diseases in open-access papers, as found by Europe PMC text mining. Sharing a sentence is not in itself a finding about the gene and the disease.
CYP3A51P shares sentences with these, for which no sentence is quoted: breast carcinoma (1 paper); stomach adenocarcinoma (1); Stroke (1).